RNU2-31P (RNA, U2 small nuclear 31, pseudogene)
Gene: Small nuclear RNA gene on chromosome 3 (159,808,416 to 159,808,570, reverse strand). Ensembl gene ENSG00000252763.
Homologues: Orthologues: pig U2 (55% identical), dog U2 (42% identical), dog U2 (39% identical), rat LOC120093485 (39% identical), guinea pig U2 (36% identical), rabbit U2 (32% identical), rabbit U2 (30% identical), tropical clawed frog U2 (28% identical). Paralogues in human: RNU2-56P (62% identical), U2 (62% identical), RNU2-64P (61% identical), RNU2-2 (61% identical), RNU2-48P (61% identical), RNU2-14P (59% identical), RNU2-17P (59% identical), RNU2-59P (59% identical), RNU2-32P (59% identical), RNU2-33P (59% identical), RNU2-4P (59% identical), RNU2-6P (59% identical), and 64 more.